INS (insulin)
Diseases named in the same sentence as INS in open-access papers (continued):
Sharing a sentence is not in itself a finding about the gene and the disease.
Osteopenia (17 papers, 2010 to 2025). Osteopenia is a term to define bone density that is not normal but also not as low as osteoporosis. "Our goal in the current study was to unravel the cellular and molecular mechanisms that underlay osteopenia in the naturally occurring T1DM NOD mouse model, and their response to insulin treatment." (PMID 33977201, 2021). "Aging skeletal muscle exhausts bone marrow cells particularly when insulin returns from its lifetime peak, which contributes osteopenia and the eventual death of old rats." (PMID 33744845, 2021). "In humans living with T1DM, the incidence of osteoporosis or osteopenia was found to be significantly higher in patients before insulin treatment." (PMID 31575077, 2019). "However, in groups with T1DM and osteopenia in the femoral neck, a significant statistical difference was noted in the daily dose of insulin." (PMID 41282295, 2025). "After binding with the osteocalcin receptor GPRC6A in muscle, it may influence osteopenia by promoting glucose metabolism, lipid metabolism, insulin secretion, expression and exercise-induced IL-6 secretion." (PMID 40771224, 2025). "Although the etiology of skeletal abnormalities in T1DM is multifactorial, uncontrolled glucose levels and the lack of insulin are considered the main causes for T1DM‐associated osteopenia." (PMID 33977201, 2021). "Here, we reported that the serum levels of insulin, c-peptide and IGF-1 were lower in diabetic untreated animals that control non-diabetic ones, which suggest the enrolment of insulin/IGF-1 in diabetic osteopenia." (PMID 34371877, 2021). "The role of metabolic control in osteopenia is still not well established despite that some data suggest that insulin, growth factors or osmotic factors such as extra-cellular glucose levels may play a significant role in the osteoblast metabolism." (PMID 20205769, 2010).
Polyuria (17 papers, 2019 to 2025). An increased rate of urine production. "Polyuria and impaired insulin signaling induced by disorders of glucose metabolism can increase macrophage infiltration and secrete inflammatory cytokines, leading to local and systemic inflammation." (PMID 37702622, 2023).
respiratory failure (17 papers, 2009 to 2025). The significant impairment of gas exchange within the lungs resulting in hypoxia, hypercarbia, or both, to the extent that organ tissue perfusion is severely compromised. "We suggest that high insulin requirements in this disease relate to its propensity to cause severe respiratory failure in patients with pre‐existing metabolic disease." (PMID 34268452, 2021). "In conclusion, high insulin requirements in severe COVID‐19 likely relate to the severity of respiratory failure and the high prevalence of metabolic disease in patients with severe illness." (PMID 34268452, 2021). "However, within a few hours, the patient’s condition rapidly deteriorated to a stuporous mental status and respiratory failure despite intensive hydration and insulin therapy for DKA." (PMID 40859516, 2025). "It is interesting to speculate on the pathophysiological mechanisms linking severity of respiratory failure to insulin requirements in viral pneumonitis." (PMID 34268452, 2021). "Model 1 was a crude model without covariate-adjusted; Model 2 was adjusted for all identified confounding variables, including cardiogenic shock, respiratory failure, SAPSII, SOFA, GCS, CCI, SPO2, platelet, total bilirubin, vasopressor, antibiotics, and insulin." (PMID 40773463, 2025). "The use of insulin in patients with coexisting COPD and T2D may require attention to the possibility of respiratory failure." (PMID 37242426, 2023). "Patients without respiratory or cardiovascular failure, those with respiratory failure without CIH, and those with respiratory failure and CIH had a linear increase in c-peptide:BG ratios (0.015, 0.038 and 0.08, respectively) consistent with increasing elevations in insulin resistance." (PMID 19245691, 2009).
thyrotoxicosis (17 papers, 2011 to 2026). A hypermetabolic syndrome caused by the elevation of thyroid hormone levels in the serum. "Meanwhile, thyrotoxicosis is known to increase insulin degradation and glucagon secretion, both of which contribute to the development of DKA." (PMID 41322011, 2025). "In thyrotoxicosis, increased glucose production combined with insulin resistance enhances the body's reliance on lipolysis for energy, resulting in further ketone body production." (PMID 39980893, 2025). "GI losses of potassium can result from diarrhea or vomiting and inter-cellular shift of potassium can result from insulin administration, sympathetic overstimulation and thyrotoxicosis." (PMID 40654398, 2024). "Glucose intolerance in thyrotoxicosis is usually accompanied with an increase in insulin secretion, which is often considered to be a compensatory response." (PMID 36302774, 2022). "To conclude, thyrotoxicosis is an insulin-resistant state, despite lower weight and reduced whole body fat mass." (PMID 35929907, 2022). "In this case, thyrotoxicosis induced by checkpoint inhibitors worsened his blood glucose control so that he needed more insulin injections." (PMID 29914537, 2018). "Thyrotoxicosis has been reported to increase endogenous glucose production in the liver in the basal state and to decrease hepatic insulin sensitivity in humans." (PMID 21941681, 2011). "Indeed, increased insulin secretion has been noticed in thyrotoxicosis in some early studies, which was usually considered as a compensatory response to lower the elevated blood glucose levels." (PMID 36302774, 2022). "Although ketoacidosis may result per se from the insulin resistance present in thyrotoxicosis, the stimulatory action of thyroid hormones in excess on lipolysis and free fatty acids availability can also contribute to increased ketogenesis." (PMID 21941681, 2011). "Glucose tolerance and insulin secretion have been investigated in patients with different thyroid status and experimental hypo- and hyperthyroid animal models, but not yielding a consistent explanation, which is likely due to the severity or duration of thyrotoxicosis or hormone treatment." (PMID 36302774, 2022). "Additionally, thyrotoxicosis results in an increase in insulin clearance." (PMID 35106234, 2021).
Addison’s disease (16 papers, 2008 to 2025). "Other potential complications include panhypopituitarism, primary adrenal insufficiency, and insulin-deficient diabetes." (PMID 39859105, 2025). "Glucose, insulin, ACTH and cortisol concentrations during glucagonstimulation test (morning hydrocortisone dose omitted) in a 20-year-oldfemale patient with Addison’s disease before and after OCPwithdrawal." (PMID 39700335, 2024).
autonomic neuropathy (16 papers, 2012 to 2026). An inherited or acquired peripheral neuropathy affecting the autonomic nervous system. "The reported association between sleep disruption and type 2 diabetes is believed to be related to energy homeostasis, insulin resistance, beta-cell function and autonomic neuropathy." (PMID 41425203, 2025). "The highest prevalence of autonomic neuropathy was seen in the group of adolescents featuring the highest longitudinal HbA1c levels, and total insulin dose, age, triglyceride levels and previous smoking increased the relative risk of developing autonomic neuropathy." (PMID 41219438, 2026). "Autonomic neuropathy increases the prevalence of SIBO as well as insulin requirements." (PMID 36615748, 2022). "One could anticipate that patients with T2D and albuminuria have advanced autonomic neuropathy, which can diminish the vasoconstrictive effects of insulin." (PMID 31119456, 2019). "In the absence of autonomic neuropathy, there is synchrony between vasodilatory and vasoconstrictive effects of insulin in maintaining appropriate blood flow." (PMID 31119456, 2019). "The findings from our study suggest that, even in well controlled T2DM patients with no symptoms of autonomic neuropathy, melatonin rhythms are blunted relative to BMI-matched individuals who exhibit normal insulin sensitivity." (PMID 22623983, 2012).
cataract (16 papers, 2012 to 2026). Partial or complete opacity of the crystalline lens of one or both eyes that decreases visual acuity and eventually results in blindness. "Despite insulin supplementation and possible residual C-peptide in CDM, many dogs remain severely dysglycemic, with weight loss, cataracts, and chronic and recurrent infections." (PMID 41816348, 2026). "Nutritive soy isoflavones drastically enhanced insulin biosynthesis thereby ameliorating excessive blood sugar and as well mitigated diabetic complication such as cataracts." (PMID 38035005, 2023). "Additionally, a positive correlation was observed between insulin dose (IU/kg/day) and cataract score in saline-treated Wfs1 KO rats (R2 = 0.396, p < 0.01) and in liraglutide-treated Wfs1 KO rats (R2 = 0.271, p < 0.05)." (PMID 34831417, 2021). "Moreover, these methionine-restricted rodents not only show greater activity but also prolonged good health with both a lower incidence and delay in age-onset of cancer, cataracts, inflammation, and insulin insensitivity." (PMID 29679203, 2018). "Since PINS was a protective factor for the lens and fundus in our study, one might suppose that intensive insulin therapy might improve ocular lesions and postpone the onset of cataracts and retinopathy." (PMID 28656153, 2017). "Moreover, a combination of vitamin E, a lipid-soluble and antioxidant vitamin, and insulin could prevent the formation and progression of cataracts in the animals." (PMID 32879893, 2020).
esophageal cancer (16 papers, 2012 to 2026). A primary or metastatic malignant neoplasm involving the esophagus. "This study found that GLP-1 RAs, compared to insulin, were associated with a significant reduction in esophageal cancer risk (HR, 0.60; 95% CI, 0.42–0.86)." (PMID 40182628, 2025). "An elevated risk of esophageal cancer appeared in DM patients taking insulin (OR 2.57, 95% CI 1.08-6.15) or sulfonyurea (OR 3.80, 95% CI 1.16-12.5)." (PMID 23234272, 2012). "Current glucose management for patients with esophageal cancer predominantly focuses on insulin pharmacotherapy, but medication‐based approaches carry hypoglycemic risks and have limitations in regulating metabolic disorders." (PMID 41403470, 2025). "It was also shown that physical activity reduces fasting insulin C-peptide and IGF-1, as well as lowering inflammatory cytokines, and increases adiponectin, reducing the risk of gastric and esophageal cancers." (PMID 39766104, 2024). "Recent studies have also further highlighted the potential central role of Akt in Barrett’s oesophageal cancer progression: signalling via the insulin/insulin-like growth factor-1 axis and HER2 receptor also activates Akt along the Barrett’s dysplasia-cancer sequence." (PMID 33582946, 2021). "Key focus areas include its impact on insulin signaling, AMP-activated protein kinase (AMPK) activation, and the mTOR pathway, which collectively contribute to its role in mitigating esophageal cancer progression." (PMID 38474224, 2024). "Notably, insulin pharmacotherapy also fails to address stress‐induced metabolic disturbances, which are common in patients with postoperative esophageal cancer due to surgical trauma." (PMID 41403470, 2025).
human papillomavirus infection (16 papers, 2019 to 2025). "Top 5 of KEGG pathway enrichment analysis was “PI3K-Akt signaling pathway”, “MAPK signaling pathway”, “Human papillomavirus infection”, “mTOR signaling pathway”, “Insulin signaling pathway”." (PMID 36366842, 2023).
hypopituitarism (16 papers, 2018 to 2026). A condition of diminution or cessation of secretion of one or more hormones from the anterior pituitary gland. "The precise role of BCAAs in hypopituitarism, whether they are mere consequences, causative factors or mere biomarkers of impaired insulin response, remains to be elucidated." (PMID 40032645, 2025). "Clinical characteristics, replacement therapy, insulin sensitivity and body composition of patients with hypopituitarism." (PMID 31447781, 2019). "Identifying etiological factors contributing hypothalamic obesity may lead to multi-faceted interventions targeting hyperphagia, insulin resistance, decreased energy expenditure, sleep disturbance, hypopituitarism and psychosocial morbidity." (PMID 35464063, 2022). "In the absence of multiple pituitary hormone deficiencies in neonates, an inappropriately large glycemic response to glucagon stimulation may be considered diagnostic, particularly when plasma insulin concentration is low." (PMID 37454648, 2024). "However, elevated levels of fasting triglycerides, total cholesterol, glucose, insulin and HOMA‐IR were noted in individuals with hypopituitarism compared to the control group." (PMID 40032645, 2025). "Patients with hypopituitarism without GH replacement showed significant lower levels of fasting glycemia, insulin and HOMA-IR." (PMID 31447781, 2019). "Decreased insulin sensitivity in patients with hypopituitarism without GH replacement (pHP-WGHR) remains conflicting in literature." (PMID 31447781, 2019). "Decreased in insulin sensitivity has been noted in patients with hypopituitarism without GH replacement (pHP-WGHR), an alteration attributed to the GHD." (PMID 31447781, 2019).
infarction (16 papers, 2009 to 2025). A localised pathological necrosis of tissue resulting from obstruction of the blood supply usually by a thrombus, an embolus, or vascular torsion. "In conclusions, impaired insulin sensitivity and reduced muscle strength were independently associated with a higher risk for silent lacunar infarcts, and the combination of both synergistically elevated this risk in Japanese elderly individuals." (PMID 34702849, 2021). "The underlying mechanisms linking impaired insulin sensitivity, reduced muscle strength, and silent lacunar infarcts are not yet fully understood." (PMID 34702849, 2021). "Thus, the present study suggested that two muscle characteristics, strength and insulin sensitivity, are independently and synergistically associated with silent lacunar infarcts." (PMID 34702849, 2021). "Additionally, the lowest muscle strength group was associated with a higher OR for silent lacunar infarcts even with adjustment for insulin sensitivity and other parameters in model 3 (High, 1.00 [reference]; Medium, 1.40 [95% CI 0.98–2.02]; Low: 1.49 [95% CI 1.04–2.15], p for trend 0.037)." (PMID 34702849, 2021). "We also evaluated the combined effect of insulin sensitivity and muscle strength on silent lacunar infarcts." (PMID 34702849, 2021). "Exogenous insulin supplementation significantly improved glucose uptake via co-activation of myocardial AMPK and Akt and alleviated ischemia/reperfusion injury as evidenced by reduced myocardial apoptosis and infarction size in STZ-treated rats (P<0.05)." (PMID 23922853, 2013).
pulmonary arterial hypertension (16 papers, 2011 to 2025). Pulmonary arterial hypertension (PAH) is a group of diseases characterized by mean pulmonary artery pressure >20 mmHg and elevated pulmonary arterial resistance leading to right heart failure. "A recent study has reported that the up-regulation of SELENOP is related to an increase in insulin resistance and exercise resistance, a decrease in insulin secretion and the proliferation of smooth muscle cells in pulmonary hypertension." (PMID 34142161, 2021). "Several literature reports showed that the chronic use of phosphodiesterase-5 inhibitors enhances the insulin sensitivity, improves the markers of endothelial function, and helps in the treatment of severe extremity ischemia and pulmonary hypertension." (PMID 32454833, 2020). "The serotonylation of the same proteins is also involved in insulin secretion and in the proliferation of pulmonary vascular smooth muscle cells and thereby in the pathogenesis of pulmonary arterial hypertension (PAH)." (PMID 31824263, 2019). "Recent reports have also suggested a link between insulin resistance with pulmonary arterial hypertension." (PMID 21513515, 2011). "In addition, serotonylation presents an important molecular event promoting disease progression in many physiological and pathological processes, such as platelet activation, insulin secretion, and formation of pulmonary arterial hypertension." (PMID 37046308, 2023).
transient ischemic attack (16 papers, 2012 to 2025). A brief attack (from a few minutes to an hour) of cerebral dysfunction of vascular origin, with no persistent neurological deficit. "It is reported that an increase in phosphorylated eIF2α occurs in hippocampal neurons of rats exposed to transient cerebral ischemia, while insulin administration can almost completely eliminate the phosphorylation of eIF2α in this model." (PMID 22403710, 2012).
amyotrophic lateral sclerosis (15 papers, 2009 to 2025). Amyotrophic lateral sclerosis (ALS) is a neurodegenerative disease characterized by progressive muscular paralysis reflecting degeneration of motor neurons in the primary motor cortex, corticospinal tracts, brainstem and spinal cord. "The top pathways in Landrace were endocytosis and signaling pathways including cGMP-PKG, cAMP, estrogen signaling pathways, adrenergic signaling in cardiomyocytes, insulin secretion, thyroid hormone synthesis, aldosterone synthesis, amyotrophic lateral sclerosis, and purine metabolism." (PMID 32184802, 2020).
autonomic dysfunction (15 papers, 2006 to 2024). "We previously conducted a cross-sectional study that showed an association of autonomic dysfunction with decreased insulin sensitivity, though involvement of autonomic function in the association between napping and insulin sensitivity remained unclear." (PMID 38027100, 2023). "Results obtained in the present study showed that a nap time of greater than one hour was independently associated with decreased insulin sensitivity related to autonomic dysfunction." (PMID 38027100, 2023). "Furthermore, we previously reported findings of a cross-sectional study indicating that autonomic dysfunction is associated with decreased insulin sensitivity." (PMID 38027100, 2023). "Furthermore, insulin resistant individuals with impaired fasting glucose have previously shown cardiac autonomic dysfunction, and a pathogenic link between increased oxidative stress, low-grade chronic inflammation and cardiac autonomic dysregulation was proposed." (PMID 25906397, 2015). "Recently, in a study published by the laboratory group, the authors showed that autonomic dysfunction assessed by baroreflex sensitivity in the offspring of parents with a high-fructose diet was also correlated with reduced insulin sensitivity." (PMID 39204159, 2024). "Diabetic patients need aggressive glycemic control to decrease insulin-related hyper-progesterone and prevent nerve complications with autonomic dysfunction." (PMID 35743808, 2022). "The findings of this study support the hypothesis that autonomic dysfunction is a major factor in the development of decreased insulin sensitivity." (PMID 26277879, 2015).